IGHV3-64 (immunoglobulin heavy variable 3-64)
Description:
V region of the variable domain of immunoglobulin heavy chains that participates in the antigen recognition. Immunoglobulins, also known as antibodies, are membrane-bound or secreted glycoproteins produced by B lymphocytes. In the recognition phase of humoral immunity, the membrane-bound immunoglobulins serve as receptors which, upon binding of a specific antigen, trigger the clonal expansion and differentiation of B lymphocytes into immunoglobulins-secreting plasma cells. Secreted immunoglobulins mediate the effector phase of humoral immunity, which results in the elimination of bound antigens. The antigen binding site is formed by the variable domain of one heavy chain, together with that of its associated light chain. Thus, each immunoglobulin has two antigen binding sites with remarkable affinity for a particular antigen. The variable domains are assembled by a process called V-(D)-J rearrangement and can then be subjected to somatic hypermutations which, after exposure to antigen and selection, allow affinity maturation for a particular antigen.
Synonyms: IGHV364; VH
Gene: Immunoglobulin variable (V) gene on chromosome 14 (106,657,725 to 106,658,258, reverse strand). Ensembl gene ENSG00000223648.
Subcellular location: Secreted; Cell membrane
Gene Ontology:
Molecular function: antigen binding
Biological process: immunoglobulin mediated immune response
Cellular component: extracellular region; plasma membrane
Homologues: Paralogues in human: IGHV3-23 (91% identical), IGHV3-64D (91% identical), IGHV3-74 (88% identical), IGHV3OR16-10 (87% identical), IGHV3-66 (86% identical), IGHV3OR16-13 (86% identical), IGHV3-53 (86% identical), IGHV3-43 (85% identical), IGHV3-48 (85% identical), IGHV3-21 (83% identical), IGHV3-30 (83% identical), IGHV3-33 (83% identical), and 65 more.
Diseases named in the same sentence as IGHV3-64 in open-access papers:
IGHV3-64 is named in the same sentence as 2 diseases in open-access papers, as found by Europe PMC text mining. Sharing a sentence is not in itself a finding about the gene and the disease. The quoted sentences say what the papers report.
Stroke (1 paper, 2025). Sudden impairment of blood flow to a part of the brain due to occlusion or rupture of an artery to the brain. "In a proteomics stroke study, researchers identified ICAM-2, STXBP5, PLGLA, C3, and IGHV3-64 as candidate biomarkers in blood, yielding a high (75% to 88%) sensitivity for identifying stroke patients." (PMID 40362186, 2025).
cancer (2 papers, 2016 to 2023). A tumor composed of atypical neoplastic, often pleomorphic cells that invade other tissues. "Currently, some studies have explored the biological functions of IGHV3-64 in other cancers." (PMID 37670814, 2023). "Two genes, RABL6 (a GTP-binding member of the Ras superfamily of small GTPases) and IGHV3-64, have not previously been reported in mutated form in human cancer." (PMID 27997540, 2016). "Based on the WGS data for 13 patients and TES data from an expanded cohort of 69 T-ALL cases that were integrated with LOH data, we identified 151 mutated genes, of which two genes had not been observed before in human cancer (RABL6 and IGHV3-64)." (PMID 27997540, 2016).